AKT1 (AKT serine/threonine kinase 1)
Diseases named in the same sentence as AKT1 in open-access papers (continued):
Sharing a sentence is not in itself a finding about the gene and the disease.
cancer (continued). "Indeed, adenoviral delivery of this peptide into intact cancer cells blocks both pressure-activated signaling and consequent increases in cell adhesion without interfering with other aspects of FAK or Akt1 signaling." (PMID 29228673, 2017). "Overall, our results suggest that targeting at the PI3K or AKT1/2 level would not be effective in preventing tumor progression, although specifically targeting AKT2-driven signals could be more effective at preventing cancer aggressiveness." (PMID 28287129, 2017).
tumor (4,751 papers, 2002 to 2026). "Mutation at E17K in the PH domain of AKT1 mediates sustained activation of AKT1 and its downstream pathways, promoting tumor formation." (PMID 40918508, 2025). "The abnormal activation of AKT1 is not only closely associated with tumor progression but also involved in tumor resistance mechanisms to chemotherapy, radiotherapy, and targeted therapies." (PMID 40573220, 2025). "Whole genome sequencing of the patient’s tumour identified various mutations including AKT1 and NOTCH1, as well as the TP63-TBL1XR1 gene fusion." (PMID 40715645, 2025). "The significantly higher frequency of NF1, ACVR1, MAP2K1, and AKT1 mutations in EOCRC H/L patient data support the call for expanded investigation into their biological significance in tumor development and treatment response." (PMID 40227607, 2025). "In our study, PIK3CA and AKT1 mutations were associated with smaller tumor size and more uniform texture, although these associations did not meet the strict criteria for significance after Bonferroni correction." (PMID 40002579, 2025). "To investigate the impact of the AKT T21A mutation on tumor cell proliferation and tumor immunity, we measured in vitro cell proliferation in AKT1 T21A knock‐in CT26 and LLC cells." (PMID 38229183, 2024). "Collectively, these findings demonstrate that phosphorylation and cytoplasmic accumulation of ME2fl is strongly tumorigenic and is likely an important mechanism underlying the effect of AKT1 in tumor cells." (PMID 38263319, 2024). "Among the PIK3CA mutation-positive tumor samples with AKT data (CB n = 7, NCB n = 5), the amount of AKT present per 10 μg total protein ranged from 0.6 to 4.5 fmol for AKT1 and 0.6 to 2.0 fmol for AKT2." (PMID 38954770, 2024). "An analysis of the underlying mechanism identified a total of 21 interacting proteins implicated in tumor formation, and among these, AKT1, CDK4, GNB2, and MAPK8 were confirmed at both gene and protein levels." (PMID 39336799, 2024). "Research has shown that AKT1 is closely linked to the differentiation, invasion, and metastasis of early-stage tumor cells." (PMID 39598341, 2024). "After that, a group of primary tumor cells acquired six additional mutations (in genes AKT1, BCL9L, B2M, FBXW7, MUTYH, RSPO2)." (PMID 38685065, 2024). "When categorized by mutation status, the median tumour volumes were 22 cm3 for AKT1, 22 cm3 for SMO/SUFU, and 42 cm3 for WT (p < 0.05)." (PMID 38672677, 2024). "Systemic Akt1 ablation, on the other hand, blocks metastasis by inhibiting the mobilization and survival of tumor-associated neutrophils, which have pro-metastatic properties; ablating Akt1 in neutrophils alone is sufficient to impede metastasis." (PMID 39614261, 2024). "Again, none of the three CTNNB1 (c.65_100del, c.94G > C, and c.100G > A) and AKT1 (c.49G > A) mutations in the initial LBC sample were found in the tumour tissue by deep sequencing." (PMID 39516270, 2023). "In the present work, we have demonstrated that downregulated or mutated ARID1A attenuates DNA HRR by stimulating the PI3K/Akt1 pathway and renders tumor cells highly sensitive to PARPi." (PMID 36910637, 2023). "The treatment groups were also balanced for the proportion of participants whose tumours carried PIK3CA mutations versus AKT1 mutations versus PTEN alterations." (PMID 35671774, 2022). "In GBM/LGG, low expression levels of miR-637 and high expression of AKT1 generally represent tumor progression and are associated with poorer overall survival (OS) and higher clinical stage." (PMID 36175921, 2022). "Although tumor growth was significantly reduced after systematic treatment of the inhibitor, inhibition of Akt1 in M2 macrophage contributed to suppression of tumor growth, which was accelerated by SENP3 loss in macrophages." (PMID 33932085, 2022).
tumor (continued). "For example, in transgenic mice with activated Akt1 or Akt2 expression within the mammary gland, AKT1 is predominantly associated with tumor initiation, whereas AKT2 is involved in tumor progression and metastasis." (PMID 36230716, 2022). "Mechanistically, in SENP3‐deficient macrophages, Akt1 becomes hyper‐SUMOylated, followed by its hyper‐phosphorylation and activation, which contributes to M2 polarization in the tumor environment." (PMID 33932085, 2022). "This testing identified an expanded pathway-altered subgroup of FAKTION participants whose tumours carried a PIK3CA mutation or AKT1 E17K or deleterious PTEN alteration, as well as the corresponding expanded pathway non-altered subgroup." (PMID 35671774, 2022). "The network pharmacology and pathway enrichment analysis predicted that EGFR, PI3K, and AKT1 was increasingly associated pathway with the anti-tumor properties of 18α-GA in NSCLC." (PMID 36313358, 2022). "In the EAY131-Y trial, the objective response rate of single-agent capivasertib (AZD5363) was 28.6% (N=35) in patients with an AKT1 E17K-mutated tumor." (PMID 35402264, 2022). "Up to 30% of TNBC tumours harbour aberrations in the oncogenic PI3K/AKT pathway through mutation of either AKT serine/threonine kinase 1 (AKT1) or PIK3CA." (PMID 36176752, 2022). "In solid cancers, hyperactivated PI3K/Akt/mTOR signaling is either due to activating mutations in EGFR, ERBB2, PIK3CA and Akt1, or loss of function of tumor suppressor genes such as PTEN." (PMID 36358647, 2022). "Tumor cells with an activating AKT1 mutation can be targeted by AKT1 inhibitors or agents blocking mTOR, a downstream member of the AKT1 signaling pathway." (PMID 34885114, 2021). "In summary, these findings show that high UBE2S expression and active Akt1 are associated with adverse tumor characteristics." (PMID 34123793, 2021). "The loss/gain-of-function assays showed that circ-AKT1 regulated AKT1 and then promoted cell proliferation and invasion in CC in vitro, and it was verified that the tumor growth was promoted in CC by vivo assays." (PMID 33841509, 2021). "Of significance, ectopic expression of either an active form of InR (InRact) or myr-Akt1 rescued the defect in yki3S/A tumor growth caused by wg depletion." (PMID 34078667, 2021). "Thereafter, we comprehensively evaluated the associations between tumor location (embryological origin), pathological diagnosis (histological type), and driver mutations including AKT1, KLF4, SMO, POLR2A, and NF2 mutations." (PMID 33772057, 2021). "We then divided the available RCC tumor samples into low versus high expression of AKT1, AKT2 and AKT3 and performed a patient survival association analysis." (PMID 34384473, 2021). "IGF/IGF-1R signaling mediates cell proliferation, cell survival, migration, and protein synthesis and can block apoptosis by expressing Myc and Akt1 in the liver, thereby causing invasion and metastasis of tumor cells." (PMID 33669204, 2021). "The two objective responses (both PRs) in the combination cohorts are noteworthy because advanced metastatic triple-positive breast cancer is associated with treatment resistance, and AKT1 tumor alterations are associated with resistance to tamoxifen." (PMID 34407844, 2021). "The possible reason is that an AKT1 mutation can inhibit cell survival and proliferation, and promote tumor cell apoptosis." (PMID 34408553, 2021). "Loss of PTEN and AKT1 amplification or AKT1 activating mutations in tumor samples have been associated with resistance to CDK4/6i." (PMID 34072070, 2021). "The expression of AKT1 was negatively associated with tumor purity (r = −0.386, p = 1.15e-02), positively correlated with CD8+ T cells (r = 0.523, p = 4.50e-04) and neutrophils (r = 0.583, p = 6.44e-05) in infiltrating levels." (PMID 34955857, 2021). "In the MBC population of the patients, one actionable mutation—PIK3CA, ESR1, ERBB2, or AKT1—was found in ten patients and two in three cases either in the tumor or in the plasma." (PMID 34298704, 2021).
tumor (continued). "For example, AKT1-mutated tumours are found in the anterior skull base, are usually histologically meningothelial or transitional in nature, and tend to recur more quickly." (PMID 32070062, 2020). "The whole exome sequence and ctDNA mutation analysis indicated that the rate of AKT1 E17K mutation accumulation successively increased, which was consistent with tumor growth." (PMID 32997401, 2020). "The oncogene AKT1 has only one known hotspot, AKT1 E17K (c.49G>A; p.Glu17Lys), where the mutation in the pleckstrin homology domain causes constitutive AKT1 activation, enhancing cell proliferation and tumour growth." (PMID 32070062, 2020). "The molecular mechanism of how AKT1 E17K or NF2 loss influences immunosuppressive environment in the tumour is likely to involve different cell types and be more complex." (PMID 32070062, 2020). "The associations thatindicated protection for tumor bilaterality were: AKT1 (CC) +AR (A) and PI3K (GG) + AR (A)." (PMID 32484847, 2020). "Our results demonstrated that while all Akt isoforms regulate thyroid growth, Akt1 was the only isoform whose loss delayed tumor induction and local invasion." (PMID 33110146, 2020). "The researchers sequenced the whole exome of patients and found a high prevalence of the AKT1 E17K mutation (26%) in tumor tissue." (PMID 32997401, 2020). "PDX HBCx-118 (BRCA2 and AKT1 mutated) responded to the combination of AZD5363 plus fulvestrant, while PDX HBCx-142 (AKT1 and mTOR mutated) responded with tumour regression to everolimus and with stable disease to volasertib, AZD5363 and palbo + fulvestrant." (PMID 32792481, 2020). "The inhibition of IKKε in tumor cells was associated with reduced cell proliferation and resulted in the altered regulation of the NF-кB, Akt1 and MAPK pathways." (PMID 32630674, 2020). "Microarray data and subsequent immunohistochemistry (IHC) identified potential Akt1-dependent gene expression differences in tumor-associated dendritic cells (DCs) in the primary tumors." (PMID 33110146, 2020). "AKT1 was mutated in 1 tumor (1.1%) and showed one already known missense mutation affecting the Pleckstrin homology (PH) domain of the protein." (PMID 31548566, 2019). "In conclusion, whole body loss of Akt1 stunts the proliferation and activation of ECs, thus blocking retinal, corneal and tumor angiogenesis." (PMID 30984553, 2019). "High levels of pAKT1 are associated with a high grade and a high stage of the tumor, suggesting a pivotal role of AKT1 in tumor progression." (PMID 31752925, 2019). "AKT is postulated to contribute to gastric carcinogenesis and to influence prognosis, and our bioinformatic analysis of the TCGA dataset showed that there was significant upregulation of AKT3 RNA in CDH1-deficient tumours, but variable AKT1 expression." (PMID 31540244, 2019). "Inhibition of AKT can restore sensitivity to cisplatin‐resistant TGCT cells by re‐localizing p21 from the cytoplasm to the nucleus, while PIK3CA and AKT1 mutations are exclusively found in cisplatin‐resistant tumours." (PMID 31179642, 2019). "A recent multihistology basket trial of an AKT inhibitor (AZD5363) in advanced solid tumor refractory to standard therapy with AKT1 E17K mutation illustrated the utility of comprehensive tumor biomarker analysis." (PMID 31032221, 2019). "Here, we provide evidence that two activating Akt1-mutations including the clinically relevant Akt1-E17K naturally occurring in human tumours and the artificial Akt1-TDSD promote resistance to ionizing radiation." (PMID 28209968, 2017). "With recent technical advances for minimally invasive mutation detection in circulating tumor DNA (ctDNA), we subsequently also evaluated the OncoBEAMTM assay to enable plasma specimens as additional diagnostic opportunity for AKT1 E17K mutation testing." (PMID 28472036, 2017). "Five patients (20.0%) with PIK3CA altered tumors also had PTEN mutations, while 1 patient (4.0%) had a dual PIK3CA and AKT1 mutated tumor." (PMID 28178681, 2017).
tumor (continued). "The AKT1 gene is a known somatic driver kinase and this mutation was found in the cBioPortal database in 46 different samples from many different tumor types, including breast." (PMID 28569218, 2017). "We demonstrate by in silico analysis that Akt1 is the dominant isoform harbouring gain-of-function mutations, particularly the PH domain mutation E17K, in tumour samples, whereas Akt2 and Akt3 undergo copy number variations with higher frequency." (PMID 28209968, 2017). "We also investigated phosphorylation of the Akt1 protein as an indicator of the Akt1/mTOR pathway activation in 43 tumor samples in association with ZNF703 expression." (PMID 27650486, 2016). "The PI3K pathway was mutated in 46% of the tumours, with mutations in AKT1 (5.1%), PIK3R3 (2.9%), PTEN (1.4%), PIK3CB (1.4%), PIK3CG (1.4%), PIK3CD (1.4%) and PIK3CA that tended to be mutually exclusive." (PMID 26729235, 2016). "For the first patient, prestudy tumor samples from lung metastases were revealed to be Akt1 (E17K) and CTNNB1 (G34V) mutation positive." (PMID 26931343, 2016). "For example, tumor A00021 had both AKT1 E17K (27.9%) and BRAF G469A (19.7%) mutations, and tumor A00026 had both BRAF D594G (26.7%) and PIK3CA E542K (15.6%) mutations." (PMID 26989027, 2016). "Of the catalytic site inhibitors, AZD5363 has shown activity against GC cell lines in vitro, and, as a monotherapy, has mediated partial responses in two patients that harbored tumor mutations in either AKT1 or PI3KCA." (PMID 26267324, 2015). "DNA extracted from each tumor pair was used to determine PIK3CA and AKT1 mutation status with a sensitive and specific qPCR-based assay, and serial sections from each tumor pair were also used to assess Ki67 staining and total PTEN loss via IHC." (PMID 24520381, 2014). "In our study we found that loss of either Akt1 or Akt2 produced a small but significant delay in tumor onset and a small but significant decrease in tumor growth rate." (PMID 23919516, 2013). "One of the five patients (case #17) had an AKT1 mutation, and achieved tumor regression of 26% that lasted 17 months." (PMID 23765114, 2013). "To date, partial responses have been observed in two treated patients, harboring tumor mutations in either AKT1 or PI3KCA." (PMID 24088382, 2013). "PTEN underexpression was significantly mutually exclusive with PIK3CA, PIK3R1 and AKT1 mutations (p = 0.00016), as it was observed in only one AKT1 mutated tumor and 14 PIK3CA mutated tumors." (PMID 24229379, 2013). "It is probable that the loss of Akt1 or Akt2 was compensated for by the remaining Akt isoforms and/or alternative signaling pathways in the tumor cells." (PMID 23919516, 2013). "These authors observed an unexpected significant down-expression of some Akt-regulated genes such as RPS6KB1 in their PIK3CA-mutated tumor series, but a normal level of AKT1 and mTOR transcripts." (PMID 21209903, 2010). "Further study is required to fully understand which tumour types take advantage of Akt1 (E17K) mutations to activate the PI3K–AKT pathway." (PMID 19491896, 2009). "High AKT1 levels were also associated with this tumor subtype, which has been previously identified." (PMID 17663798, 2007). "For example, Akt-1 is more highly expressed in tissues such as brain, thymus and lungs, whereas Akt-2 gene amplification has been found in ovarian, breast and pancreas tumours where it has been implicated in the process of invasion and metastasis." (PMID 16721361, 2006). "Current research suggests that the AKT1 E17K mutation may play both antitumor and oncogenic roles in tumor cells." (PMID 39769140, 2024).